GPC3 (glypican 3)
Diseases named in the same sentence as GPC3 in open-access papers (continued):
Sharing a sentence is not in itself a finding about the gene and the disease.
tumor (continued). "Other serum tumor markers of HCC included des-γ carboxyprothrombin, Golgi protein 73, glypican-3, Neprilysin and AFP-L3, which did not provide better accuracy." (PMID 35193513, 2022). "Another study reported GPC3 expression by IHC in 39 out of 55 MCC cases (71%), without providing details on tumor characteristics or clinical outcomes." (PMID 35937502, 2022). "Among these, only the glypican-3 (GPC-3) appears to be highly specific for HCC, with high expression in tumor cells and low or no expression in normal cells." (PMID 35008303, 2021). "GPC3 CAR-T cells had an obvious killing effect on GPC3-positive tumor cell lines HepG2 and Huh7, while GPC3-negative tumor cell lines had no killing activity." (PMID 34527749, 2021). "GPC3‐specific CAR‐NK‐92 cells were also indicated to have an effective cytokine production and anti‐tumour activity on HCC xenografts, expressing both low and high levels of GPC3, while they were not reactive to GPC3‐negative cells." (PMID 34423899, 2021). "At immunohistochemical analysis, both tumor components were negative for germ cell markers (AFP, SALL4, and Glypican-3), while they showed distinctive expression of Müllerian and intestinal markers." (PMID 32781666, 2020). "Compared with AFP, GPC3 performs better in the early detection of HCC, and its capacity for diagnosis is not affected by the tumor size and stage." (PMID 32849835, 2020). "NK-92/9.28.ζ cells showed a potent anti-tumor activity against multiple HCC xenografts with both high and low GPC3 expression, but not in those without GPC3 expression." (PMID 32707982, 2020). "Immunohistochemical staining showed that the tumor cells were negative for AE1/AE3, CK18, CK7, CK19, Hepatocyte Paraffin-1, Glypican-3, Arginase-1, CD56, Chromogranin A, Synaptophysin, Vimentin, and Carcinoembryonic antigen." (PMID 31488173, 2019). "The tumour was found to be positive for cytokeratin 18 (CK18) and was negative for Arg-1, hepatocyte, glypican-3 (GPC-3), and CK7 in IHC analysis." (PMID 31064408, 2019). "The tumor cells were diffusely positive for AFP, CK, CK8/18, GPC-3, and hepatocyte, but negative for CD30, CD34, CK19, D2–40, PLAP, and vimentin." (PMID 29351804, 2018). "Second, the comparison between an anti-GPC3 monoclonal antibody and L5 peptide in terms of their efficacy to guide USPIO probes to tumor cells was not assessed." (PMID 30275801, 2018). "Univariate analysis showed that age, gender, tumor size, hepatic virus infection, ALT, pre-AFP, pre-PIVKA-II, and GPC3 expression by immunohistochemical staining were not significant risk factors for recurrence." (PMID 28035063, 2017). "Both serum GPC3 and AFP levels were not affected significantly by age, sex, tumor size, PRETEXT stage and the status of lymphovascular invasion or metastasis." (PMID 28378832, 2017). "Immunohistochemically, the tumor was positive for CD31, CD34, and Vimentin, a mesenchymal marker, and negative for HAS and GPC-3, which excluded the possibility of hepatocyte origin." (PMID 22280556, 2012). "In the immunohistochemical analysis, the tumor cells were positive for GATA-binding protein 3 (GATA3) and trichorhinophalangeal syndrome type 1 (TRPS1) but negative for HepPar1 and Glypican-3, which indicated that the tumor originated in the breast rather than the liver." (PMID 40994809, 2025). "Meantime, we found that OHSV2-DSTEFAP/CD3-based therapy exhibits the absence of off-tumor toxicity, including cytokine storm, inconsistent with previous studies on FAP targeting therapy and CAR-T therapy, despite GPC3 and FAP are suboptimal targets owing to their low specificity." (PMID 40406146, 2025).
tumor (continued). "Assessment of HAC markers revealed that the tumor cells were positive for AFP and glypican-3; negative for Sal-like protein 4; strongly positive for human epidermal growth factor receptor 2 (3+); positive for Brahma-related gene 1 and retinoblastoma 1; and negative for CD117 and S100." (PMID 40900781, 2025). "Interestingly, shed GPC3, existing in a soluble form, can competitively bind to CAR-GPC3 T cells without activating them, thereby impairing their anti-tumor efficacy." (PMID 38679698, 2024). "However, since the correlation between AFP, GPC3, MDK, DKK1 and FNDC4 is not high, the sensitivity of FNDC4 as a tumor marker still needs further study." (PMID 38021165, 2023). "Moreover, GPC-3-CAR/sIL-15 Vδ1 T cells displayed greater proliferation and stronger anti-tumor responses when compared with GPC-3-CAR Vδ1 T cells lacking sIL-15, suggesting IL-15 signal was critical for CAR Vδ1 T cell function." (PMID 35747139, 2022). "However, MDK and combinations of AFP + MDK, GPC3 + OPN have not been studied yet, therefore, it is a question of future research to investigate effectiveness of using these tumor markers in combination." (PMID 34513063, 2021). "The median serum levels of AFP, PIVKA-II, GPC-3, adiponectin and IL-6 were significantly higher in patients with HCC compared to those without tumor (all p < 0.001); only the plasma leptin values were not different between the two groups of patients (p = 0.649)." (PMID 34064999, 2021). "Nevertheless, GPC3 expression in LUSC samples was not significantly correlated with age, location, years smoked, pathologic M, pathologic N, pathologic T, radiation therapy, sex, or tumour stage (P > 0.05)." (PMID 34112123, 2021). "However, only the expression of TXNIP, not CYP2J2 or GPC3, was positively correlated with the expression of circDCUN1D4 in LUAD tumor tissues, confirming that TXNIP is the target of circDCUN1D4." (PMID 33425493, 2021). "When injected into GPC3-expressing orthotopic HCC PDX in NOD SCID Gamma (NSG) mice, 89Zr-Df-H3K3 showed specific high uptake into the orthotopic PDX and minimal, non-specific uptake into the non-tumor bearing liver." (PMID 34439132, 2021). "In addition, the expression of BTG2, CD69, GPC3, and IL7R were considerably elevated in tumor stages III-IV as opposed to tumor stage I-II (p < 0.05)." (PMID 34881236, 2021). "In this model, failure of significant tumor response was consequence of a lack of CD8+ T cell infiltration into the tumor and by mosaic-pattern of GPC3 expression which could be enhanced in future studies." (PMID 32899197, 2020). "Extravascular contrast-enhanced ultrasound targeted GPC3 on HCC may not be realized, and the reason may be that targeted contrast agents of microbubbles are hard to access and accumulate in the tumor stroma and matrix." (PMID 33354418, 2020). "Moreover, there was no specific CD3 staining in the tumor sections from mice which treated with UTD and GPC3-Syn-IL12-NK92 cells." (PMID 31921693, 2019). "Immunohistochemical staining showed that the tumor cells were negative for AE1/AE3, CK18, CK7, Hepatocyte Paraffin-1(Hep Par-1), Glypican-3 (GPC-3), Arginase-1 (ARG-1), CD56, Chromogranin A (CgA), Synaptophysin (Syn), Vimentin, and Carcinoembryonic antigen (CEA)." (PMID 31488173, 2019). "Moreover, the AUROCs of GPC3 for HB versus all controls and HB versus BHD were 0.63 and 0.54, respectively, suggesting that GPC3 is not an effective serum tumor marker for HB." (PMID 28378832, 2017).
tumor (continued). "Unfortunately, the main serum tumor markers including alpha-fetoprotein (AFP), lens culinaris agglutinin-reactive AFP (AFP-L3), des-gamma carboxyprothrombin (DCP) and glypican-3 (GPC3), failed to reach the optimal results when tested in the surveillance and early detection." (PMID 26933386, 2016). "In our studies, GPC3 immunoreactivity was detected in 103 of 136 HCC cases (75.7%), and GPC3 expression was closely related with HBsAg positivity, but not with sex, HCC differentiation, age, serum AFP level, tumor size, and extrahepatic metastasis." (PMID 24498024, 2014). "Immunohistochemical staining for the HCC marker, glypican 3 (GCP3) in livers harboring tumors, demonstrated positive staining in five of nine Casp2C320S and two of four Casp2−/− mice, while the two WT livers with tumor nodules were negative for GCP3, suggesting that these liver tumors were not HCC." (PMID 41477850, 2026). "transduced human T cells with a GPC3-CAR together with CXCR2; compared with CAR-T cells without CXCR2, these cells exhibited identical cytotoxicity but significantly increased migration in vitro, as well as accelerated in vivo trafficking and tumor-specific accumulation in a xenograft tumor model." (PMID 35432319, 2022). "Recent studies of HCC tumor xenografts in mice and in vitro established that engineered CAR-T cells targeting the glypican 3 (GPC3) molecule, highly expressed in HCC samples and absent in healthy liver samples, could attack and eliminate GPC3-positive HCC cells." (PMID 34065489, 2021).
cancer (252 papers, 2004 to 2026). A tumor composed of atypical neoplastic, often pleomorphic cells that invade other tissues. "This complexity calls for further research to elucidate the mechanisms underlying the dualistic behavior of GPC3 across different cancer types." (PMID 40422229, 2025). "To analyze the expression of GPC3 and its variants in malignancies, we performed expression analysis with ISOexpresso, a web-based platform for isoform-level expression analysis in cancer." (PMID 39841705, 2025). "In HCC, TAA compromise oncofetal and cancer-germline antigens such as glypican 3 (GPC3) and melanoma-associated gene C1 (MAGE-C1)." (PMID 38440738, 2024). "GPC3 is an independent risk factor for overall survival rate in patients with cancers and he incidence of MVI is higher in HCC patients with positive GPC3 expression." (PMID 36973651, 2023). "Glypican3 (GPC3), a heparan sulfate glycoprotein located on the surface of cell membranes, is a specific antigen associated with cancer." (PMID 37608298, 2023). "Of these, 143 neopeptides were derived from clonal mutations, with two originating from cancer driver genes (GPC3 and MAML2)." (PMID 35410325, 2022). "Increased expression of GPC3 can promote the proliferation and invasion of cancer cells, so it is used as a diagnostic target for tumors." (PMID 36139670, 2022). "Further studies on larger sample size, samples from other geographical regions and samples of other types of cancers are recommended to examine the associations between GPC3 −784 G/C polymorphism and cancer risk." (PMID 31053802, 2019). "GPC3 is highly expressed in HCC and considered to play a role in cancer invasion and progression; accordingly, GPC3 is also a promising diagnostic and therapeutic marker for HCC." (PMID 31706332, 2019). "The involvement of GS in liver tissue is wildly described associated with others (Glypican 3, heat shock protein 70) as biomarkers of hepatocellular tumors, particularly overexpressed in malignant tumors." (PMID 28937622, 2017). "Hypermethylation of the GPC3 promoter associated with gene silencing has been observed in certain adult cancers." (PMID 15083193, 2004). "These approaches capitalize on the specific characteristics of cancer cells, such as the overexpression of uPAR and the presence of cancer-associated antigens like GPC3, to enable precise and efficient tumor targeting, opening up new avenues for more effective and personalized cancer treatments." (PMID 37608298, 2023). "Combining anti-GPC3 antibodies and immune checkpoint inhibitors (ICIs) may be a promising strategy for GPC3-associated cancers." (PMID 35251989, 2022). "GPC3 mutations and abnormal protein expression have been linked to tissue-specific cancers." (PMID 36676710, 2022). "Given that the expression of glypicans is altered during tumorigenesis and glycoproteins have been suggested as a promising target of biomarkers in cancer, we want to determine whether GPC3 may serve as a non-invasive diagnostic and prognostic tool for GEA." (PMID 31100935, 2019). "There are several studies which have linked GPC3 with cancer." (PMID 27507057, 2016). "As the gene is located on the X chromosome and DNA methylation is implicated in chromosome X inactivation, this observation raises the possibility that a loss of methylation could be implicated in the overexpression of GPC3 in some cancer forms." (PMID 15083193, 2004). "BAY 3547926 (225Ac-GPC3) is an 225Ac-labeled antibody-chelator conjugate (ACC) that delivers 225Ac directly to GPC3-expressing cancer cells and is a potential first-in-class targeted α-therapy in advanced HCC." (PMID 41469158, 2026). "Accordingly, GPC3 has the potential to exert either a pro- or anti-oncogenic effect, contingent upon the specific cancer type." (PMID 40422229, 2025).
cancer (continued). "So far, the investigations into the anti-oncogenic mechanisms of GPC3 are still limited; thus, the application of GPC3 in cancer treatment still faces significant challenges." (PMID 40422229, 2025). "The UPSND‐mediated GPC3 CRISPR‐Cas9 therapy significantly suppresses cancer cell proliferation by modulating the Wnt and Hippo/YAP pathways." (PMID 40657181, 2025). "In GPC3-positive cancer cells, two humanized anti-GPC3 antibody-drug conjugates (hYP7 and hYP9.1b) in the IgG format have been shown to cause complement-dependent cytotoxicity as well as antibody-dependent cell-mediated cytotoxicity (ADCC)." (PMID 40416124, 2025). "They administered 5 and 10 mg/kg ZnO-NPs daily for 8 weeks and found that the treatment of these animals with these NPs resulted in the inhibition of cancer biomarkers including glypican-3 (GPC3), VEGF, and alpha-fetoprotein (AFP)." (PMID 40182988, 2025). "The suppressive effects of GPC3 on certain types of cancers align with its functions in embryonic development and within normal tissues." (PMID 40422229, 2025). "At picomolar doses, both ADCs killed GPC3-positive cancer cell lines (Hep3B, HepG2, and Huh 7); however, the PBD dimer-based ADC was 5-10 times more effective than the duocarmycin SA-based one." (PMID 40416124, 2025). "We have selected five common membrane protein cancer antigens, including GPC3, which have high cancer specificity and are frequently expressed in various cancers." (PMID 40076777, 2025). "Given its oncogenic function, GPC3 has already been suggested as a potential target for cancer immunotherapy in the treatment of HCC, including CAR-T and CAR-NK strategies." (PMID 39841705, 2025). "Representative examples of five common cancer antigens, GPC3, ROBO1, CLDN1, EphB4, and LAT1, expressed on the cell membrane of cancer cells are shown." (PMID 40076777, 2025). "GPC3, a member of the glypican family, represents a glycosylphosphatidylinositol-anchored proteoglycan located on the cell membrane of cancer cells that plays important roles in controlling cell division and regulating growth." (PMID 41154636, 2025). "For example, the median expression of these receptors in patients is often lower in the cancer tissue than in the liver or other organs, except for GPC3." (PMID 40278256, 2025). "The majority of the physiological functions of GPC3 involve the inhibition of growth factor signaling, but its pro-oncogenic effects in cancers are accomplished by facilitating the signaling of a variety of growth factors." (PMID 40422229, 2025). "We detected the cancer-specific antigen glypican 3 (GPC3) and identified peptides that can induce CTLs in a human leukocyte antigen (HLA) A24- or A2-restricted manner." (PMID 40806530, 2025). "The response rate is thought to increase if treatment is limited to cancer patients who express GPC3 on the cell membrane." (PMID 40076777, 2025). "Although ROBO1 and GPC3 are often expressed in cytoplasm, there are also cases in which they are expressed on the cell membrane depending on the type of cancer." (PMID 40076777, 2025). "Proteins such as GPC3 are classified as oncofetal antigens due to their expression during fetal development and cancer progression." (PMID 40278256, 2025). "This study also demonstrates that the interaction between GPC3 and CD26 is independent of HS chains, further providing direct evidence that the soluble form of GPC3 can exert an inhibitory effect on at least a subset of cancer cells." (PMID 40422229, 2025). "While the dual role of GPC3 in cancer development is recognized, the mechanism governing this duality remains elusive." (PMID 40422229, 2025). "The ectopic expression of GPC3 in cell lines originating from these cancer types inhibits cancer cell proliferation and/or induces apoptosis." (PMID 40422229, 2025).